SPINK5 (serine peptidase inhibitor Kazal type 5)
Description:
Serine protease inhibitor, probably important for the anti-inflammatory and/or antimicrobial protection of mucous epithelia. Contribute to the integrity and protective barrier function of the skin by regulating the activity of defense-activating and desquamation-involved proteases. Inhibits KLK5, its major target, in a pH-dependent manner. Inhibits KLK7, KLK14 CASP14, and trypsin.
Synonyms: LEKTI; VAKTI; LETKI; NETS; NS; FLJ21544; FLJ97536; FLJ97596; FLJ99794; DKFZp686K19184
Tractability: Antibody: its Gene Ontology location is reachable by antibodies, with high confidence; UniProt places it where antibodies can reach, with medium confidence; UniProt predicts a signal peptide or a membrane-spanning region.
Gene: Protein-coding gene on chromosome 5 (148,025,683 to 148,137,382, forward strand). Ensembl gene ENSG00000133710.
Subcellular location: Secreted
Subcellular location (Human Protein Atlas): Vesicles; Predicted to be secreted
Pathways (Reactome):
Developmental Biology: Differentiation of Keratinocytes in Interfollicular Epidermis in Mammalian Skin; Formation of the cornified envelope
Gene Ontology:
Molecular function: serine-type endopeptidase inhibitor activity; peptidase inhibitor activity
Biological process: epidermal cell differentiation; cell differentiation; epithelial cell differentiation; extracellular matrix organization; hair cell differentiation; negative regulation of angiogenesis; negative regulation of immune response; regulation of T cell differentiation; regulation of timing of anagen; negative regulation of antibacterial peptide biosynthetic process; negative regulation of antibacterial peptide production
Cellular component: cell cortex; cytoplasm; cytosol; endoplasmic reticulum; endoplasmic reticulum membrane; epidermal lamellar body; extracellular region; perinuclear region of cytoplasm
Genetic constraint (gnomAD): Loss-of-function variants: 120 observed, 153.86 expected, observed/expected ratio (o/e) 0.78, 90% interval 0.67 to 0.91. The upper end of that interval is the gene's LOEUF score, 0.91, which puts it in group 3 of 6, group 1 being the genes least tolerant of losing a copy. Missense variants: 1,161 observed, 1,317 expected, observed/expected ratio (o/e) 0.88, 90% interval 0.84 to 0.93. Synonymous variants: 365 observed, 407.73 expected, observed/expected ratio (o/e) 0.9, 90% interval 0.82 to 0.98.
Gene-disease validity (ClinGen):
ClinGen rates the evidence that SPINK5 causes each of these diseases.
Netherton syndrome (autosomal recessive): Definitive. Netherton syndrome (NS) is a skin disorder characterized by congenital ichthyosiform erythroderma (CIE), a distinctive hair shaft defect (trichorrhexis invaginata; TI) and atopic manifestations.
Homologues: Orthologues: chimpanzee SPINK5 (98% identical), macaque SPINK5 (94% identical), dog SPINK5 (80% identical), rabbit SPINK5 (78% identical), pig SPINK5 (73% identical), rat Spink5 (62% identical), mouse Spink5 (61% identical), guinea pig SPINK5 (59% identical). Paralogues in human: FSTL5 (9% identical), FSTL4 (9% identical), FST (8% identical), FSTL3 (5% identical), FSTL1 (5% identical), SPINK6 (4% identical).
Diseases named in the same sentence as SPINK5 in open-access papers:
SPINK5 is named in the same sentence as 103 diseases in open-access papers, as found by Europe PMC text mining. Sharing a sentence is not in itself a finding about the gene and the disease. The quoted sentences say what the papers report.
Netherton syndrome (84 papers, 2005 to 2025). "This is evident from the fact that loss-of-function mutations in the SPINK5 gene cause Netherton syndrome, which is characterized by severe barrier dysfunction." (PMID 41375188, 2025). "Netherton syndrome is an autosomal recessive genodermatosis caused by loss-of-function mutations within the SPINK5 (serine protease inhibitor Kazal-type 5) gene." (PMID 40899446, 2025). "Netherton syndrome is an autosomal recessive genodermatosis caused by biallelic mutations in the SPINK5 gene, a gene that codes for lymphoepithelial Kazal-type-related inhibitor 1 (LEKT1) protein." (PMID 41487865, 2025). "Netherton syndrome (NS) is a rare autosomal recessive disorder resulting from loss-of-function mutations in the SPINK5 gene, a gene encoding the serine protease inhibitor of Kazal-type 4 (LEKTI)." (PMID 39189180, 2024). "Since Netherton syndrome was suspected at the age of 2 years and 8 months, the SPINK5 gene mutation was tested by DNA-sequence." (PMID 39917683, 2024). "Netherton syndrome (NS) is a rare skin disease caused by loss-of-function mutations in the serine peptidase inhibitor Kazal type 5 (SPINK5) gene." (PMID 38316920, 2024). "Netherton syndrome is caused by a genetic mutation causing loss of function of the SPINK5 gene it encodes for the LEKTI protein, normally expressed in epithelia." (PMID 38025195, 2023). "Comel–Netherton syndrome is characterized by an ichthyosiform AD–like pattern, a bamboo–like hair–shaft defect and multiple atypical manifestations, caused by SPINK5 mutations." (PMID 36672710, 2023). "SPINK5 is involved in the regulation of proteolysis in epithelial formation and keratinocyte terminal differentiation, whereas mutations in human SPINK5 cause a distinctive defect in skin barrier function in Netherton syndrome." (PMID 37723525, 2023). "The loss of kallikrein inhibition via decreases in serine protease inhibitor Kazal type-5 (SPINK5) leads to Netherton syndrome, in which patients demonstrate impaired barrier function with epidermal hyperplasia and symptoms of atopic dermatitis." (PMID 38067173, 2023). "Netherton syndrome (NS) is a rare autosomal recessive disorder caused by SPINK5 mutations, resulting in a deficiency in its processed protein LEKTI." (PMID 37239440, 2023). "Genetic testing revealed a mutation in the SPINK5 gene, which had confirmed the diagnosis with Netherton syndrome." (PMID 35327681, 2022). "Netherton syndrome (NS; OMIM#256500), also known as Comel-Netherton syndrome, is a rare autosomal recessive disorder caused by germline loss-of-function mutations in SPINK5 gene." (PMID 36569942, 2022). "LOF mutations in SPINK5, the gene encoding LEKTI, lead to the Netherton syndrome with congenital ichthyosis, abnormal hair shafts, and severe atopy also extending beyond the skin." (PMID 35572516, 2022). "SPINK5 (serine peptidase inhibitor, Kazal type 5) are associated with Netherton syndrome (OMIM#256500), a disorder involving skin and hair abnormalities and a high risk of allergies, asthma, and an inflammatory skin condition, eczema." (PMID 36268024, 2022). "Three patients clinically diagnosed with HIES had homozygous mutations in SPINK5, which cause Comèl–Netherton syndrome, a rare syndrome associated with erythroderma, ichthyosis, short and brittle “bamboo” hair, atopy, and elevated IgE." (PMID 34390440, 2021). "Netherton syndrome, a rare skin disease caused by loss of function mutations in the SPINK5 gene, has also been the target of autologous skin grafts pre-clinically and on a phase I clinical trial." (PMID 34684016, 2021). "In Family C, a homozygous splice site variant (c.882 + 1G > T) in SPINK5, was identified, causing Netherton Syndrome." (PMID 33807935, 2021). "PKP1 interacts with desmosomal proteins and regulates desmosomal turnover and signaling, and the interaction between DSG1 and SPINK5 is evidenced by increased DSG1 degradation in mice deficient in SPINK5 as a model of Netherton syndrome, a skin disorder." (PMID 32735560, 2020).
Netherton syndrome (continued). "The SPINK5 gene encodes LEKTI which is involved in the pathogenesis of AD-like disorders, such as Netherton syndrome, a syndrome characterized by severe dermatitis, allergic diseases, and high serum IgE levels." (PMID 31408293, 2019). "In the skin, kallikrein‐related peptidases are controlled by SPINK5 and unopposed kallikrein‐peptidase activity due to SPINK5 deficiency leads to Netherton syndrome, a severe skin disease." (PMID 28554943, 2017). "Loss-of-function mutations in SPINK5 leads to enhanced skin kallikrein activities and cause the skin disease Netherton Syndrome (NS)." (PMID 27824929, 2016). "Netherton Syndrome is caused by mutations in SPINK5 encoding the serine protease inhibitor known as the lympho-epithelial Kazal-type-related inhibitor (LEKTI), and this has specific clinical parallels to AD patients." (PMID 28025545, 2016). "This phenomenon is in line with findings for the SPINK5 gene, in which null mutations cause autosomal recessive Netherton syndrome while common variations have been associated with AD." (PMID 25363238, 2014). "Mutations in the human SPINK5 (LEKTI) gene lead to Netherton syndrome characterized by abnormal desquamation and impaired cornification." (PMID 24699552, 2014). "Spink proteins are serine protease inhibitors involved in skin barrier formation: mutations in the Spink5 –LEKTI- gene in humans cause the Netherton syndrome, an ichthyosiform dermatosis; Spink5 KO mice have severe alteration in the Stratum Corneum (SC)." (PMID 21072181, 2010). "For example, mutations in SPINK5 gene encoding the serine protease inhibitor lympho-epithelial Kazal-type inhibitor (LEKTI) cause Netherton syndrome associated with chronic skin inflammation and skin barrier defects." (PMID 20805888, 2010). "For example, while mutations in SPINK5, causes Netherton syndrome, a rare autosomal recessive disorder, SPINK5 also plays a role in common atopic diseases." (PMID 19534795, 2009). "Mutation in SPINK5 causes Netherton syndrome, a rare recessive skin disease that is accompanied by severe atopic manifestations including atopic dermatitis, allergic rhinitis, asthma, high serum IgE and hypereosinophilia." (PMID 19534795, 2009). "Mutations in the SPINK5 gene (encoding another protease inhibitor) are responsible for Netherton syndrome (OMIM #256500), characterized by ichthyosiform erythroderma, bamboo hair and atopic dermatitis." (PMID 17562024, 2007). "Our findings suggest that Netherton syndrome may be underestimated clinically, and our findings further expand the reservoir of SPINK5 mutations in Netherton syndrome." (PMID 36159989, 2022). "LEKTI can diminish the activities of epidermal serine proteases such as KLK5, KLK6, KLK7, KLK13, and KLK14 in skin, and a mutation in the SPINK5 gene is characteristic of Netherton syndrome, which presents with serious dehydration, itching, and chronic skin inflammation." (PMID 35955819, 2022). "A similar phenotype may be produced by genetic skin disorders such as Comèl–Netherton syndrome, an ichthyosis syndrome caused by mutations in SPINK5 encoding, a serine protease essential for skin barrier integrity." (PMID 34390440, 2021). "Importantly, the upregulation of KLK5 and KLK7 activity by loss of the endogenous KLK inhibitor serine peptidase inhibitor Kazal type 5 (SPINK5) causes atopic dermatitis‐associated diseases, including Netherton syndrome." (PMID 29311134, 2018). "The remaining three patients had Netherton syndrome (one case due to SPINK5 mutations), erythrokeratoderma (one case due to GJB3 mutation), and KLICK (keratosis linearis with ichthyosis congenita and sclerosing keratoderma) syndrome (one case carrying POMP mutation)." (PMID 29618363, 2018). "SPINK5 encodes an inhibitor of multiple serine proteases, including plasmin, neutrophil elastase, and trypsin, and mutations in this gene have been associated with Netherton syndrome." (PMID 28552993, 2017).
Netherton syndrome (continued). "In Netherton syndrome, which is caused by loss-of-function mutations in SPINK5 encoding for LEKTI, an aberrant KLK5 protease activity in patients with this syndrome causes extensive skin desquamation, inflammation, allergic manifestations, and hair shaft defects." (PMID 29077044, 2017). "Loss-of-function mutations in SPINK5 cause the rare genetic skin disease Netherton Syndrome (NS)." (PMID 27824929, 2016). "Furthermore, Spink5 has been identified as the gene causing Netherton’s Syndrome, and there are case reports of patients with this disease also having papillomatous skin lesions and cutaneous malignancies." (PMID 25474466, 2014). "Because Netherton syndrome exhibits allergic phenotype, it is reasonable to speculate that SPINK5, which is mutated in Netherton syndrome, may act as a candidate gene for asthma and other allergic diseases." (PMID 19534795, 2009). "Loss of function mutations in the SPINK5 gene cause Netherton syndrome, characterized by congenital ichthyosis with defective cornification, and severe atopic manifestations including atopic dermatitis, allergic rhinitis, asthma, markedly elevated serum IgE and hypereosinophilia." (PMID 19534795, 2009). "Netherton syndrome (NS) is a rare, autosomal recessive disease resulting from a mutation in the pathogenic variants in the Kazal type 5 (SPINK5) gene." (PMID 40969297, 2025). "Netherton syndrome (NS) is a rare autosomal recessive syndrome caused by mutations in the serine protease inhibitor of the Kazal type 5 (SPINK5) gene." (PMID 40471236, 2025). "Netherton syndrome (NS) is a rare, autosomal recessive genodermatosis disorder caused by biallelic mutations in the SPINK5 gene." (PMID 41487865, 2025). "Netherton syndrome (NS) is a rare autosomal recessive disorder that occurs due to a loss-of-function mutation in SPINK5; this loss results in significant inflammation, as well as perturbations of the skin barrier’s integrity and functionality." (PMID 39189180, 2024). "Netherton Syndrome (NS) is an autosomal recessive-inherited type of ichthyosis where genetic mutations in the SPINK5 gene results in the loss of function of lymphoepithelial Kazal-type-related serine protease inhibitor (LEKTI-1)." (PMID 37081873, 2023). "SPINK5 deficiency leads to Netherton syndrome (NS) characterized by impaired skin barrier function, epidermal hyperplasia, hair abnormalities, chronic skin inflammation, and atopic dermatitis." (PMID 35223512, 2022). "Netherton syndrome (NS), a syndromic form of ichthyosis, is caused by loss of function mutation in the serine protease inhibitor of Kazal type 5-gene (SPINK5, OMIM #256500)." (PMID 33652877, 2021). "Aside from AD, S. epidermidis overexpansion and EcpA production are also linked to exacerbation of Netherton syndrome (NS), a skin disorder characterized by high levels of serine protease activity caused by a mutation in the gene SPINK5." (PMID 33180890, 2020). "Netherton syndrome (NS) is a rare life-threatening syndrome caused by SPINK5 mutations leading to a skin barrier defect and a severe atopic diathesis." (PMID 30477583, 2018). "Netherton syndrome (NS), a rare autosomal recessive disorder, is due to a mutation in the epidermal gene SPINK5 encoding the proteases inhibitor protein LEKTI." (PMID 29056696, 2017). "In this direction, a skin equivalent (encompassing both epidermis and dermis) for SPINK5-sEDD (Netherton syndrome) was previously designed, to test the role of KLK7 and KLK5 gene silencing, or their chemical inhibition in reversing the disease phenotype." (PMID 40943523, 2025). "LEKTI is a major KLK5 inhibitor, and functional variants of the SPINK5 gene cause Netherton syndrome, which is characterized by three main symptoms: ichthyosis, hair abnormalities, and an atopic constitution." (PMID 41375188, 2025). "Netherton syndrome is a rare, autosomal recessive disorder caused by SPINK5 gene mutations, leading to LEKTI protein deficiency." (PMID 40899446, 2025).
Netherton syndrome (continued). "These symptoms highly resemble the symptoms of SPINK5-sEDD (formerly Netherton syndrome, OMIM 256500)." (PMID 40943523, 2025). "Netherton syndrome (NS) is a rare autosomal recessive hereditary disease caused by the mutation of the SPINK5 gene, which encodes the Serpin LEKTI (lymphoepithelial Kazal-related inhibitor)." (PMID 40969297, 2025). "Combined transcriptomics and proteomics of skin and lymphoid organs reveal the significance of SPINK5 in the regulation of protease activity and systemic inflammation, providing a conserved molecular framework for Netherton syndrome." (PMID 38316920, 2024). "For example, the skin inflammation and scaling characteristic of Netherton syndrome is caused by loss-of-function mutations in SPINK5, which encodes the epidermal serine protease inhibitor LEKTI." (PMID 35327667, 2022). "Reduced expression or activity of SPINK5 in Netherton syndrome increases the activities of serine proteases that impair cohesion in the SC, which leads to SC thinning, delayed skin repair, and dehydration and has fatal consequences for fetuses." (PMID 35955819, 2022). "Defects in the SPINK5 gene lead to Netherton Syndrome, an uncommon autosomal recessive disease characterized by severe ichthyosis, atopic dermatitis (AD), congenital thyroid dysfunction, and bamboo-like hair symptoms." (PMID 35955819, 2022). "On the other hand, ILC is quite different from Netherton syndrome which associates ILC with a specific hair-shaft abnormality and rather caused by mutations in SPINK5 gene." (PMID 34983512, 2022). "Our results suggest that LCE and diosmetin are good candidates for the treatment of skin barrier-disrupting diseases such as Netherton syndrome or AD, and that they do so by regulating SPINK5/LEKTI." (PMID 35955819, 2022). "One of the well-known examples is the severe autosomal recessive form of ichthyosis, Netherton syndrome, caused by a defect in the serine-specific inhibitor Kazal type 5 (SPINK5) gene encoding LEKTI." (PMID 32054030, 2020). "Here, we show that genetic activation of the transcription factor nuclear factor (erythroid-derived 2)-like 2 (Nfe2l2/Nrf2) in keratinocytes of Spink5 knockout mice, a model for Netherton syndrome, significantly alleviates their cutaneous phenotype." (PMID 32457102, 2020). "SPINK5 specifically inhibits KLK5, KLK7, and KLK14 activity, and mutations in SPINK5 cause Netherton Syndrome, a severe skin disorder." (PMID 28414719, 2017). "Previous studies have illustrated that SPINK5 is in connection with Netherton syndrome (NS) and may play an active biological role in the coagulation process." (PMID 37185487, 2023). "LEKTI is known to be an important molecule for the skin barrier function, as demonstrated by the fact that mutations in the gene of SPINK5, which encodes LEKTI protein, resulting in Netherton syndrome." (PMID 37731494, 2023). "Recent research on SPINK5 has focused on polymorphisms of the SPINK5 gene and its effects on the clinical symptoms of Netherton syndrome, and relatively few studies have been conducted on natural products or single compounds that modulate or increase SPINK5 expression." (PMID 35955819, 2022). "At the beginning, Netherton syndrome and Erythrokeratoderma variabilis phenotypes were suspected, but no hair shaft abnormalities were found and no mutations in SPINK5 and EKV genes (GJB2, GJB3, GJB4, GJB6 and KDSR) were identified (data not shown)." (PMID 34983512, 2022). "The deregulation on some KLKs activity caused by the mutation in the SPINK5 gene, which leads to the malformation of the endogenous inhibitor of KLKs LEKTI, is directly related to the phenotype of Netherton Syndrome, which affects the health and social life of patients." (PMID 35356049, 2021). "Netherton syndrome is a severe genetic disorder associated with unregulated proteolytic activity, caused by the absence of functional LEKTI, a protease inhibitor encoded by SPINK5 gene." (PMID 28095415, 2017).